MAP2K3 (mitogen-activated protein kinase kinase 3)
Description:
Dual specificity kinase. Is activated by cytokines and environmental stress in vivo. Catalyzes the concomitant phosphorylation of a threonine and a tyrosine residue in the MAP kinase p38. Part of a signaling cascade that begins with the activation of the adrenergic receptor ADRA1B and leads to the activation of MAPK14.
Synonyms: SAPKK-2; SAPKK2; MEK3; MKK3; PRKMK3; MAPKK3
Tractability: Small molecule: a high-quality ligand is known; it belongs to a druggable protein family. PROTAC: ubiquitination databases record sites on it; its protein half-life has been measured; a small molecule that binds it is known.
Target class: STE protein kinase group; Kinase; Enzyme; Protein Kinase; STE protein kinase STE7 family
Gene: Protein-coding gene on chromosome 17 (21,284,672 to 21,315,240, forward strand). Ensembl gene ENSG00000034152.
Subcellular location (Human Protein Atlas): Cytosol; Nucleoplasm
Pathways (Reactome):
Cellular responses to stimuli: Oxidative Stress Induced Senescence
Disease: Uptake and function of anthrax toxins
Immune System: activated TAK1 mediates p38 MAPK activation
Gene Ontology:
Molecular function: MAP kinase kinase activity; protein binding; protein kinase binding; protein serine kinase activity; protein tyrosine kinase activity; ATP binding; protein kinase activity
Biological process: cellular response to vascular endothelial growth factor stimulus; negative regulation of hippo signaling; p38MAPK cascade; positive regulation of blood vessel endothelial cell migration; positive regulation of DNA-templated transcription; positive regulation of protein kinase activity; stress-activated protein kinase signaling cascade; cellular senescence; MAPK cascade; signal transduction; cellular response to lipopolysaccharide; cellular response to sorbitol; heart development; regulation of intracellular signal transduction; response to ischemia
Cellular component: membrane; cytoplasm; cytosol; nucleoplasm
Genetic constraint (gnomAD): Loss-of-function variants: 30 observed, 40.96 expected, observed/expected ratio (o/e) 0.73, 90% interval 0.55 to 0.99. The upper end of that interval is the gene's LOEUF score, 0.99, which puts it in group 4 of 6, group 1 being the genes least tolerant of losing a copy. Missense variants: 380 observed, 433.22 expected, observed/expected ratio (o/e) 0.88, 90% interval 0.81 to 0.95. Synonymous variants: 189 observed, 153.77 expected, observed/expected ratio (o/e) 1.23, 90% interval 1.09 to 1.39.
Homologues: Orthologues: macaque MAP2K3 (100% identical), dog MAP2K3 (99% identical), guinea pig MAP2K3 (97% identical), mouse Map2k3 (97% identical), rat Map2k3 (97% identical), pig MAP2K3 (83% identical), rabbit MAP2K3 (63% identical). Paralogues in human: MAP2K6 (76% identical), MAP4K4 (30% identical), STK3 (30% identical), STK4 (30% identical), TNIK (30% identical), MINK1 (29% identical), PAK2 (29% identical), STK10 (29% identical), NRK (28% identical), PAK3 (28% identical), PAK1 (28% identical), SLK (28% identical), and 23 more.
Diseases named in the same sentence as MAP2K3 in open-access papers:
MAP2K3 is named in the same sentence as 110 diseases in open-access papers, as found by Europe PMC text mining. Sharing a sentence is not in itself a finding about the gene and the disease. The quoted sentences say what the papers report.
breast carcinoma (13 papers, 2010 to 2025). "A novel loss of MAP2K3 genomic copy number was observed in breast cancer patients and the overexpression of MAP2K3 inhibited breast cancer cell proliferation by promoting cell cycle arrest." (PMID 33660414, 2021). "However, recent research has demonstrated that the loss of MAP2K3 copy number occurs in NSCLC and that MAP2K3 inhibits cell proliferation and promotes cellular senescence in hepatocellular carcinoma, breast cancer, and melanoma." (PMID 33660414, 2021). "Breast cancer patients showing elevated expression of MAP2K3 have worse survival rates, particularly triple-negative, and the kinase is proposed to be oncogenic in driving MYC in certain patients." (PMID 41152984, 2025). "For example, MAP2K3 (MKK3) has been proposed as a tumor suppressor in breast cancer thus suggesting that the inhibition of p38MAPK signaling pathway could be counterproductive in this type of tumors." (PMID 27446920, 2016). "MAP2K3 and MAP3K7 belong to the MAPK pathway, and activation of the MAPK pathway in breast cancer promotes proliferation, anti-apoptotic influence, and contributes to drug resistance, cancer cell survival, and invasion." (PMID 40426890, 2025).
hepatocellular carcinoma (7 papers, 2013 to 2025). A malignant tumor that arises from hepatocytes. "For example, miR-21 can target the MAP2K3 gene directly during the carcinogenesis of hepatocellular carcinoma, resulting in expression inhibition of MAP2K3." (PMID 29498680, 2018). "Interestingly, MAP2K3 is a direct target of miRNA-21 and miRNA-21 mimics can effectively inhibit MAP2K3 expression in hepatocellular carcinoma." (PMID 31585536, 2019). "We next sought to explore whether miR-21 was capable of regulating MAP2K3 in hepatoma cell, HepG2 cells were infected with Ad/pri-miR-21 and Ad/miR-21/inhibitor adenoviral vectors." (PMID 24112539, 2013).
colon cancer (6 papers, 2015 to 2022). "Previous findings have suggested an important role for MAP2K3 in tumor invasion and progression, such as in colon cancer." (PMID 33660414, 2021).
glioma (6 papers, 2011 to 2024). A benign or malignant brain and spinal cord tumor that arises from glial cells (astrocytes, oligodendrocytes, ependymal cells). "We analyzed somatic mutations in glioma patients from the TCGA cohort to investigate the mechanisms associated with MAP2K3 expression levels." (PMID 38938778, 2024). "By analyzing somatic mutations in glioma patients in the TCGA cohort, we found more somatic mutations in the high MAP2K3-expressing group." (PMID 38938778, 2024). "Higher levels of MAP2K3 were found to be linked with poor outcomes in low-grade gliomas, gliomas across all WHO grades, as well as recurrent tumors." (PMID 38938778, 2024). "These discoveries establish a theoretical foundation for exploring the biological mechanisms underlying MAP2K3 and its potential applications in glioma treatment." (PMID 38938778, 2024). "This kinase possesses biological functions consistent with a role in oncogenesis, as up-regulation of MAP2K3 is associated with the invasion and progression of breast tumors and gliomas." (PMID 22203497, 2011). "In our study, MAP2K3 expression was discovered to be aberrantly high in a range of tumor tissues, and such high expression was found to be associated with poor clinicopathological characteristics and outcome of gliomas." (PMID 38938778, 2024). "Additionally, MAP2K3 expression in gliomas displayed associations with a range of immune cells, and showed links with numerous immune checkpoints, implying its potential significance in determining patient responsiveness to immunotherapy." (PMID 38938778, 2024). "This suggests a potential association between MAP2K3 and the malignant behavior of gliomas." (PMID 38938778, 2024). "As a result, MAP2K3 may be employed as a glioma diagnostic marker." (PMID 38938778, 2024). "We used the single-cell RNA sequencing database TISCH to further validate MAP2K3 expression in gliomas." (PMID 38938778, 2024). "We found higher levels of MAP2K3 expression in multiple glioma cohorts with WHO grade 3 gliomas than WHO grade 2." (PMID 38938778, 2024). "We then assessed the protein expression level of MAP2K3 in gliomas using The Human Protein Atlas database." (PMID 38938778, 2024). "The outcomes of the single cell transcriptome sequencing study completely corroborated our earlier findings and present a macroscopic view of MAP2K3 in glioma." (PMID 38938778, 2024). "Through the regulation of the infiltration of immune cells, MAP2K3 can affect the prognosis of patients with glioma." (PMID 38938778, 2024). "By analyzing the TCGA database, multiple clinical study cohorts and single cell sequencing sets, we found that MAP2K3 mRNA expression was elevated in gliomas and closely correlated with tumor grade." (PMID 38938778, 2024). "Univariate Cox regression analysis showed that MAP2K3 expression, WHO staging, and age were associated with the prognosis of glioma." (PMID 38938778, 2024). "Based on the previous assessment of MAP2K3 in the glioma tumor microenvironment, we evaluated the impact of MAP2K3 expression levels on tumor immunotherapy." (PMID 38938778, 2024). "In conclusion, we found that MAP2K3 is expressed at high levels in gliomas and that high MAP2K3 expression predicts poor prognosis in glioma patients." (PMID 38938778, 2024). "All these related expression indicators were elevated suggesting that glioma patients with high MAP2K3 expression levels respond better to immunotherapy." (PMID 38938778, 2024). "Our study unveiled substantial involvement of MAP2K3 in gliomas, indicating the potential of the enzyme to serve as a prognostic biomarker related to immunity." (PMID 38938778, 2024). "To analyze Hallmarker pathway differences between gliomas with two different MAP2K3 expression levels, we performed GSVA gene enrichment analysis." (PMID 38938778, 2024). "We also used the GEPIA2 website to examine the TCGA database in order to investigate the expression of MAP2K3 in gliomas and healthy brain tissues." (PMID 38938778, 2024).
glioma (continued). "Another important finding of this study was the correlation between MAP2K3 expression and the level of immune infiltration in gliomas." (PMID 38938778, 2024). "To investigate the potential biological mechanisms of MAP2K3 in gliomas, we explored the function of MAP2K3 molecules in multiple cancer-related signaling pathways in the TCGA cohort." (PMID 38938778, 2024). "The analysis of 17 distinct transcriptome sequencing datasets of glioma single cells from various cell types revealed the presence of MAP2K3." (PMID 38938778, 2024). "These insights point towards the potential of MAP2K3 as a prognostic indicator for gliomas, and predictive biomarker for immunotherapy responses." (PMID 38938778, 2024). "By performing univariate and multivariate Cox regression analyses, we found that high MAP2K3 expression was an independent predictor of prognosis in glioma patients." (PMID 38938778, 2024). "According to the results of immunohistochemical staining, glioma tissues generally express more MAP2K3 than healthy brain tissues do, and high-grade gliomas express more of the MAP2K3 protein." (PMID 38938778, 2024). "We evaluated the localization of MAP2K3 protein in the glioma cell line SH-SY5Y, and the results showed that MAP2K3 was localized in the cytoplasm." (PMID 38938778, 2024). "In summary, we observed a marked overexpression of MAP2K3 in gliomas, correlating with the WHO classification system." (PMID 38938778, 2024). "Taken together, our research highlights the critical function of MAP2K3 in tumor immune modulation and glioma prognosis; indicating the MAP2K3 gene as a potential novel target for the treatment of glioma." (PMID 38938778, 2024). "To explore the expression pattern of MAP2K3 in gliomas, we first analyzed the expression of MAP2K3 in tumor tissues." (PMID 38938778, 2024). "The Transwell assay demonstrated that the invasive capacity of U251 glioma cells was reduced by MAP2K3 knockdown." (PMID 38938778, 2024). "Among them, MAP2K3 expression levels were higher in male patients, young and middle-aged glioma patients, and glioma patients with 1p/19q present." (PMID 38938778, 2024). "It was also established by analysis of survival data from numerous clinical cohorts that glioma patients with high MAP2K3 expression had considerably shorter survival periods and shorter progression-free survival than those with low expression." (PMID 38938778, 2024). "MAP2K3 is expressed in various glioma cell lineages and its expression is most abundant in immune and malignant cells, of which we show representative single cell sequencing datasets (GSE102130, GSE163108_10X, and GSE148842)." (PMID 38938778, 2024). "To further explore the biological pathways of gliomas at both MAP2K3 expression levels, we performed KEGG enrichment analysis on the high MAP2K3-expressing and low MAP2K3-expressing groups of the TCGA cohort." (PMID 38938778, 2024). "Survival analysis further suggested regulatory correlations: elevated expression of FAM18A-AS1 and miR-21 was associated with poor prognosis in low-grade glioma, and high expression of EGFR, WEE1, MAP2K3, JA1, and EPHA2 was associated with poor prognosis." (PMID 35296768, 2022). "We then proceeded with in vitro experiments to delve into the role of MAP2K3 in glioma cells." (PMID 38938778, 2024). "In addition, the expression level of MAP2K3 in gliomas correlated with the WHO grade of glioma, and the expression level of MAP2K3 in gliomas increased with the grade of glioma." (PMID 38938778, 2024). "There are several shortcomings of this study: First, MAP2K3 expression was only validated at the mRNA level, not at the protein level or cellular level, and ex vivo experiments are needed to further validate the possible signaling pathways involved in MAP2K3 in glioma." (PMID 38938778, 2024).
glioma (continued). "By analyzing multiple GBM cohorts and LGG cohorts, we found that MAP2K3 expression levels differed among glioma patients by age, 1p/19q co-deletion and gender; with higher MAP2K3 expression levels in young and middle-aged (<60 years), 1p/19q non-co-del, and male glioma patients." (PMID 38938778, 2024). "Recent research has indicated that unconventional levels of expression of the MAP2K3 gene closely correlates with glioma malignancy, hinting it could be a potential immunotherapy target." (PMID 38938778, 2024). "In addition, by analyzing multiple cohorts, we found that MAP2K3 expression levels in gliomas correlated with various clinical characteristics such as age, gender, and 1p/19q mutation status." (PMID 38938778, 2024). "This suggests that high levels of MAP2K3 may convey immunosuppressive effects by activating the TGFβ signaling pathway, thus promoting immune escape in gliomas with high MAP2K3 expression levels." (PMID 38938778, 2024). "The Nomogram and calibration curves demonstrate that MAP2K3 is an independent prognostic factor that accurately predict patient prognosis at 1, 3, and 5 years; indicating that MAP2K3 is a good predictor of prognosis for glioma patients in the multiple regression model." (PMID 38938778, 2024). "MAP2K3 expression levels were also upregulated in the single-cell EXP0059 glioma cell group." (PMID 38938778, 2024). "Finally, we discovered a relationship between MAP2K3 expression and immunological checkpoints, immune-related genes, and immune infiltration in glioma." (PMID 38938778, 2024). "This study also suggests that MAP2K3 may be a novel biomarker for prognosis prediction and immune checkpoint inhibitor therapy in glioma." (PMID 38938778, 2024). "MAP2K3 may regulate immunity in gliomas by interacting with or modulating immune checkpoints." (PMID 38938778, 2024). "In addition, multiple tumor immune microenvironment scores were higher in the high MAP2K3 expression group, all suggesting a more active immune microenvironment in glioma patients with high levels of MAP2K3 expression and possibly a better response to immunotherapy." (PMID 38938778, 2024). "According to the Ivy Glioblastoma Atlas Project, MAP2K3, CD68 and CD276 were found to be upregulated in human glioma samples in the Perinecrotic zone (CTpnz) region of expression." (PMID 38938778, 2024). "Multivariate Cox regression analysis revealed that MAP2K3 expression, WHO staging, and age were independent prognostic factors affecting glioma prognosis." (PMID 38938778, 2024). "We discovered through a multiple cohort survival study that patients with high expression levels of MAP2K3 had shorter overall survival, regardless of whether they had high- or low-grade gliomas." (PMID 38938778, 2024). "The mechanism by which MAP2K3 may function biologically in gliomas is not yet known." (PMID 38938778, 2024).
Obesity (6 papers, 2015 to 2024). Accumulation of substantial excess body fat. "miR-21a-5p promoted BPA-induced obesity in vivo while BPA-induced preadipocyte differentiation is repressed by miR-21a-5p by targeting map2k3 in the MKK3/p38/mitogen-activated protein kinase (MAPK) pathway." (PMID 32723695, 2020). "Eleven autoantibodies were significantly elevated in cases versus controls in the second cohort, including proteins in which genetic polymorphisms had been associated with diabetes or obesity in Pima Indians (anti-PPARG2 and anti-MAP2K3, respectively)." (PMID 26606528, 2015). "The candidate genes MIF, MAP2K3, HACD3, and MEGF11 excavated in this study are related to obesity and fat deposition." (PMID 39330807, 2024). "Moreover, associations with MAP2K3 and PPARG2 antibodies were attenuated after adjustment for BMI, supporting a hypothesis that obesity itself (with or without diabetes) may produce an adaptive immune response." (PMID 26606528, 2015).
esophageal cancer (5 papers, 2016 to 2023). A primary or metastatic malignant neoplasm involving the esophagus. "Through transfection of siRNAs specific for MAP2K3 and GADD45B, as well as plasmids harboring full-length human MAP2K3 and GADD45B sequences, we found MAP2K3 and GADD45B inhibited esophageal cancer cell proliferation." (PMID 32873775, 2020). "Microarray results showed the influence of SFE on esophageal cancer cells was related with stearoyl-CoA desaturase (SCD), cadherin 3 (CDH3), mitogen-activated protein kinase kinase 3 (MAP2K3) and growth arrest and DNA damage inducible beta (GADD45B)." (PMID 32873775, 2020).
glioblastoma (5 papers, 2020 to 2024). The most malignant astrocytic tumor (WHO grade IV). "In addition, according to the Ivy Glioblastoma Atlas Project database, the distribution of MAP2K3 was consistent with the distribution of macrophage markers CD68 and CD276." (PMID 38938778, 2024).
Sepsis (5 papers, 2014 to 2025). Sepsis is defined as life-threatening organ dysfunction caused by a dysregulated host response to infection. "Additionally, Mitogen-Activated Protein Kinase Kinase 3 (MKK3) has been unveiled to serve a critical function in the mitochondrial biosynthetic process within sepsis murine models." (PMID 38702721, 2024).
Alzheimer disease (4 papers, 2018 to 2025). A progressive, neurodegenerative disease characterized by loss of function and death of nerve cells in several areas of the brain leading to loss of cognitive function such as memory and language. "MAP2K3, also known as MKK3, is associated with cellular senescence and has been implicated in Alzheimer’s disease and age-related memory decline." (PMID 40940954, 2025). "This preliminary work suggests MAP2K3 may represent a novel therapeutic target for age-related memory decline and perhaps Alzheimer’s disease (AD)." (PMID 29896098, 2018).
Hyperglycemia (4 papers, 2011 to 2024). An increased concentration of glucose in the blood. "In streptozotocin-induced and db/db diabetic mice, hyperglycemia promotes direct binding of RAGE to mitogen-activated protein kinase kinase 3 (MKK3) and initiates assembly of the MEKK3-MKK3-p38 signaling module, which subsequently accelerates activation of the p38/NF-κB pathway." (PMID 38137892, 2023).